PIK3R3 (phosphoinositide-3-kinase regulatory subunit 3)
Diseases named in the same sentence as PIK3R3 in open-access papers (continued):
Sharing a sentence is not in itself a finding about the gene and the disease.
melanoma (10 papers, 2012 to 2025). A malignant, usually aggressive tumor composed of atypical, neoplastic melanocytes. "Studies have shown that dysregulation of PIK3R3 is strongly linked to tumor cell migration and invasion, with elevated levels of PIK3R3 enhancing melanoma cells’ migratory and invasive capabilities." (PMID 41170188, 2025). "We found that PIK3R3 has already been reported as a miR‐224‐5p target in melanoma, where it regulates cancer cell proliferation, migration, and invasion." (PMID 39840666, 2025). "miRNA-224-5p can be regulated by E2F1 to drive EMT through TXNIP downregulation in melanoma, and it can inhibit uveal melanoma cell proliferation, migration, and invasion by targeting PIK3R3/AKT3." (PMID 32993558, 2020). "Mir-137 can inhibit the migration and invasion of melanoma cells 45–47 by targeting various mRNAs such as PIK3R3, TBX3, c-Met, YB1, EZH2, and MITF, and inhibit the proliferation and promote the apoptosis of melanoma cells by competitive binding to genes such as SLC1A5, GLO1, CDK6, etc.." (PMID 33194692, 2020). "Interestingly, PIK3R3 was exclusively detected in melanoma cells, with low or undetectable expression in normal melanocytes." (PMID 22948084, 2012). "Oleacein in melanoma cells reduces the mRNA expression of c-KIT, K-RAS, and PIK3R3, which are crucial effectors responsible for heightened mTOR activation." (PMID 39203892, 2024). "These are EGFR, ERRFI1, IL6, JAK2, PLXNC1, RGL3 which were found to be upregulated and CBL, CDC42, PIK3R3, STAT3, UBE2D2 and YWHAZ which were found to be downregulated; Melanoma has PLXNC1 as upregulated and TGFA as downregulated gene." (PMID 34764329, 2021).
gastric cancer (9 papers, 2012 to 2025). A primary or metastatic malignant neoplasm involving the stomach. "Likewise, PIK3R3 mutations have been detected in various cancers, and overexpression has been found to correlate with advanced stage and metastasis in gastric cancer, confirming its prognostic potential." (PMID 39825568, 2025). "PIK3R3 is involved in regulating phosphatidylinositol 3-kinase activity and overexpressed in some types of cancers, such as colorectal, lung, and gastric cancer." (PMID 34366863, 2021). "Previous studies have shown that the gene PIK3R3 is involved in cancer development, such as gastric cancer, ewing Sarcoma and metastatic colorectal cancer." (PMID 28813538, 2017). "PIK3R3 was significantly up-regulated in gastric cancer specimens, and 9.5% to 15% tumors showed more than 2 fold increase compare to the paired mucosa tissues." (PMID 25003395, 2014). "Furthermore, the expression of PIK3R3 increased in neoplastic tissues compared to non neoplastic in patients with gastric cancer." (PMID 33329703, 2020). "In addition, comparing to gastric cancer patients with lower PIK3R3 expression, higher expression leads to poorer outcome." (PMID 30430424, 2019). "According to our GSE54129 dataset, the expression level of BPTF was increased in gastric cancer and furthermore, BPTF formed DRLs with PPM1L, NKX6.3 and PIK3R3." (PMID 35421923, 2022). "Additionally, when PIK3R3 was overexpressed in AGS cells, a low PIK3R3-expressing gastric cancer cell line, we did not observe any significant change in phosphorylation of Akt (data not shown)." (PMID 22876838, 2012).
glioblastoma (8 papers, 2010 to 2023). The most malignant astrocytic tumor (WHO grade IV). "The p55γ regulatory subunit of PI-3 kinase, Pik3r3, was recently found to be overexpressed in glioblastoma multiforme (GBM) brain tumors and has been implicated in promoting the growth of highly aggressive GBMs that lack amplification of the EGF receptor." (PMID 20520772, 2010). "Our study disclosed that circ_PTN could sequester miR-542-3p to boost PIK3R3, so as to stimulate PI3K/AKT signaling, contributing to the cisplatin resistance of glioblastoma cells." (PMID 34853725, 2021).
cervical carcinoma (5 papers, 2019 to 2025). A carcinoma arising from either the exocervical squamous epithelium or the endocervical glandular epithelium. "Western blot showed that when the expression level of FTO in cervical cancer cells was downregulated, the expressions of PIK3R3 were also decreased, as well as p‐AKT." (PMID 39692250, 2024). "All these results suggested that FTO facilitated cervical cancer malignancy through inducing m6A‐demethylation of PIK3R3 mRNA." (PMID 39692250, 2024). "Our experiment displayed that FTO can promote proliferation and migration in cervical cancer cells, and upregulation of PIK3R3 can partially neutralize the effect of FTO‐knockdown." (PMID 39692250, 2024). "Taking our findings together, the upregulation of m6A demethylase FTO decreases m6A modification of PIK3R3 mRNA, which increases PIK3R3 levels and activates FoxO pathway, thus facilitating cervical cancer malignancy." (PMID 39692250, 2024). "The results evoked that upregulation of FTO promoted the translation of PIK3R3, which enhanced the activation of FoxO pathway and facilitates cervical cancer malignancy." (PMID 39692250, 2024). "After knocking down FTO, upregulation of PIK3R3 can restore the malignancy of cervical cancer." (PMID 39692250, 2024). "Our data verified that PIK3R3 overexpression can partially reverse the inhibitory effect of FTO knockdown on proliferation, migration and invasion of cervical cancer cells." (PMID 39692250, 2024). "To further illustrate that PIK3R3 and p‐AKT is regulated by FTO in cervical cancer cells, we transfected control plasmid and PIK3R3 plasmid into SiHa‐lv‐shFTO cells, respectively." (PMID 39692250, 2024). "PIK3R3 is a regulatory subunit of PI3K, whose differential expression can promote the proliferation, invasion, and migration process of NSCLC cells, cervical carcinoma cells, and pancreatic cancer cells." (PMID 30823895, 2019). "Therefore, we take PIK3R3 as the breakthrough point to further explore the mechanism of FTO promoting the proliferation and metastasis of cervical cancer." (PMID 39692250, 2024).
glioma (5 papers, 2012 to 2025). A benign or malignant brain and spinal cord tumor that arises from glial cells (astrocytes, oligodendrocytes, ependymal cells). "When analyzing the prognostic value of PIK3R3 in GBM using the data from TCGA and CGGA databases, we found that high PIK3R3 expression was significantly associated with a poorer survival probability in gliomas (P < 0.0001)." (PMID 37644421, 2023). "Mechanistic analysis revealed that circ_0021350 sponged miR-1207-3p to regulate PIK3R3, whose overexpression reversed the reduction in the malignant biological behavior of glioma cells caused by silencing circ_0021350." (PMID 37644421, 2023). "Therefore, PIK3R3 is closely associated with glioma progression and can be used as a molecular subtype marker of GBM." (PMID 37644421, 2023). "We also conducted qRT-PCR to compare the expression of PIK3R3 in the glioma cell lines and normal human astrocytes and discovered that PIK3R3 was simultaneously increased in the A172, U251, and U87 cells." (PMID 37644421, 2023). "Overexpression of PIK3R3 rescues the glioma cell phenotype upon circ_0021350 knockdown both in vitro and in vivo." (PMID 37644421, 2023). "A previous study showed that PIK3R3 gene had copy number gain in high-grade glioma, and the Comparative Genomic Hybridization (CGH) ratios for this locus were positively-correlated with proliferation signatures." (PMID 22876838, 2012). "Furthermore, the immunohistochemistry analysis of 17 glioma specimens revealed a notably higher incidence of positive expression for SOX2 and PIK3R3 in GBM tissues compared to I‐III glioma tissues." (PMID 39968701, 2025). "Moreover, RIP analysis indicated enrichment of circ_0021350, miR-1207-3p, and PIK3R3 in the glioma cells." (PMID 37644421, 2023). "In glioma, overexpression of PIK3R3 can support the growth of GBM cells by engaging IGF2 signaling in vitro, indicating that PIK3R3 is an oncogene in glioma." (PMID 34961815, 2021).
liver cancer (5 papers, 2021 to 2024). An epithelial or non-epithelial malignant neoplasm that arises from the liver. "We determined the expression of PIK3R3 in liver cancer by using TCGA data and our clinical samples and knocked it down by siRNA or overexpressing it by the lentivirus vector system." (PMID 37212524, 2023). "RNA sequence revealed that hundreds of genes were dysregulated upon PIK3R3 knockdown in liver cancer cells." (PMID 37212524, 2023). "Recently, PIK3R3 was found to be upregulated in liver cancer; it activates Akt signaling to control cancer growth by regulating CDKN1C and SMC1A." (PMID 37644421, 2023). "PIK3R3 is upregulated in liver cancer and activates Akt signaling to control cancer growth by regulation of CDNK1C and SMC1A." (PMID 37212524, 2023). "PIK3R3 promoted liver cancer growth in vitro and in vivo by controlling cell proliferation and cell cycle." (PMID 37212524, 2023). "In our study, we identified that PIK3R3 was targeted by miR-513b-5p in liver cancer cells and involved in miR-513b-5p-inhibited autophagy liver cancer cells." (PMID 34120890, 2021). "We demonstrated that miR-513b-5p attenuated autophagy during the malignant progression of liver cancer by targeting PIK3R3." (PMID 34120890, 2021). "PIK3R3 overexpression partly reversed miR-513b-5p-mediated autophagy, proliferation, and apoptosis of liver cancer cells." (PMID 34120890, 2021). "Targeting PIK3R3 could be a promising treatment strategy for liver cancer that deserves further investigation." (PMID 37212524, 2023). "Abnormal activation of PI3K/Akt signaling is common in cancer, but whether phosphoinositide‐3‐kinase regulatory subunit 3 (PIK3R3) plays a role in liver cancer is largely unexplored." (PMID 37212524, 2023). "We found that PIK3R3 was significantly upregulated in liver cancer and correlated with prognosis." (PMID 37212524, 2023). "PIK3R3 is upregulated in liver cancer and activates Akt signaling to control cancer growth by regulation of CDNK1C and SMC1A.Targeting PIK3R3 could be a promising treatment strategy for liver cancer that deserves further investigation." (PMID 37212524, 2023). "Collectively, it indicates that PIK3R3 is targeted by miR-513b-5p in liver cancer cells." (PMID 34120890, 2021). "SMC1A was partially responsible for PIK3R3 regulated function, and SMC1A overexpression rescued the impaired tumor cell growth in liver cancer cells." (PMID 37212524, 2023). "Importantly, we verified that PIK3R3‐activated Akt signaling determined the expression of CDKN1C and SMC1A, two downstream of PIK3R3 in liver cancer cells." (PMID 37212524, 2023). "Besides, PIK3R3 displayed a more pronounced variation in liver cancer compared to normal tissues, in contrast to PIK3R1 and PIK3R2.In fresh clinical samples, we confirmed that PIK3R3 was overwhelmingly upregulated in HCC compared with paired normal tissues." (PMID 37212524, 2023). "Meanwhile, PIK3R3 overexpression partly rescued the cell proliferation and blocked the cell apoptosis, which were mediated by miR-513b-5p mimic in the HepG2, Huh-7, and HCCLM3 cells, implying that PIK3R3 is involved in miR-513b-5p-inhibited autophagy liver cancer cells." (PMID 34120890, 2021).
non-small cell lung carcinoma (4 papers, 2017 to 2025). A group of at least three distinct histological types of lung cancer, including non-small cell squamous cell carcinoma, adenocarcinoma, and large cell carcinoma. "Another study in non-small cell lung cancer showed that miR-193a-5p downregulates the mTOR/PIK3R3 signaling pathway, inhibiting the migration, invasion, and EMT of NSCLC cells." (PMID 40161373, 2025). "It has been reported that ERBB4 and S6K2 are the direct targets of miR-193a-3p and that PIK3R3 and mTOR are the direct targets of miR-193a-5p in non-small-cell lung cancer." (PMID 28611587, 2017).
colon cancer (3 papers, 2020 to 2024). "In colon cancer, miR-212 functions as it exerts a tumor suppressor effect by directly targeting PIK3R3 and modulating regulating the AKT/mTOR signaling pathway." (PMID 39133165, 2024).
sarcoma (3 papers, 2015 to 2023). A usually aggressive malignant neoplasm of the soft tissue or bone. "A recent study showed that the regulatory domain of PI3K, PIK3R3, plays an important role in maintaining sarcoma stem cells and promoting migration, invasion, and chemotherapy resistance." (PMID 35761259, 2022). "Examination of a panel of Ewing Sarcoma cell lines revealed approximately 3-fold variation in PIK3R3 protein levels." (PMID 25603314, 2015). "Previous study reported that PIK3R3 is upregulated in sarcoma CSCs and invovles in maintenances of CSC properties in sarcomas." (PMID 35761259, 2022).
Bladder cancer (2 papers, 2021 to 2022). "Using lysates of 3 matched pairs of human bladder cancers and adjacent normal tissue, as well as 6 unmatched samples, we determined that tumors deficient in ARID1A protein had elevated PIK3R3 and pAKT levels." (PMID 35852858, 2022). "Our results show a potentially novel role for PIK3R3 as an oncogene in bladder cancer biology." (PMID 35852858, 2022). "Next, we sought to determine whether ARID1A deficiency correlated with PIK3R3 upregulation and PI3K/AKT pathway activation in human bladder cancers." (PMID 35852858, 2022). "PIK3R3 upregulation is necessary and sufficient for PI3K/AKT pathway activation and increased bladder cancer cell proliferation." (PMID 35852858, 2022).
chronic myeloid leukemia (2 papers, 2014 to 2022).
Insulin resistance (2 papers, 2023). Increased resistance towards insulin, that is, diminished effectiveness of insulin in reducing blood glucose levels. "This study raised a presumption of the presence of ccr-miR-29a targeting pik3r1 or ccr-miR-143 targeting pik3r3 playing likely roles in Momordica charantia saponins remitting the liver insulin resistance." (PMID 37091861, 2023). "Instead, the underlying mechanism on Momordica charantia saponins ameliorating the liver insulin resistance of common carp might be to conduct the inhibition of ccr-miR-29a targeting pik3r1 or ccr-miR-143 targeting pik3r3." (PMID 37091861, 2023).
prostate carcinoma (2 papers, 2013 to 2022). A carcinoma that arises from epithelial cells of the prostate gland. "The authors examined the association between several SNPs in PI3Ks genes (PIK3CD, PIK3C2A, PIK3R3, PIK3AP1, and PIK3C2B) and prostate cancer risk: among the five genes, only PIK3C2B showed a cluster of SNPs related to prostate cancer risk." (PMID 23658859, 2013).
uveal melanoma (2 papers, 2020 to 2022). A melanoma derived from melanocytes of the uveal tract. "In uveal melanoma, miR-224-5p expressed lower compared to normal tissue and was involved in the proliferation, invasion, and migration via regulating the expression of PIK3R3 and AKT3." (PMID 36212129, 2022).
congenital heart disease (1 paper, 2024). A heart disease that is present at birth. "As for neo-hypoplastic left heart syndrome, PIK3R3 (Phosphoinositide-3-kinase Regulatory Subunit 3, 606076) has been shown to alter the metabolic and inflammatory metabolism in the heart of neonates with congenital heart disease." (PMID 39202774, 2024).
cutaneous T-cell lymphoma (1 paper, 2024). "Notably, the team identified a gene fusion in CD4+ cutaneous T-cell lymphoma, which includes caspase recruitment domain-containing protein 11 (CARD11) and phosphoinositide-3-kinase regulatory subunit 3 (PIK3R3)." (PMID 38730483, 2024).
diabetic kidney disease (1 paper, 2022). Progressive kidney disorder caused by vascular damage to the glomerular capillaries, in patients with diabetes mellitus. "Based on the results of transcriptomics, the pathogenesis of diabetic kidney disease may involve 11 candidate differential genes: Egr1, Foxo3, Pik3r3, Fgf1, Sost, Wnt10a, Tgif2, Akt2, Mep1b, Col1a1, Apoe." (PMID 36249745, 2022).
Ewing sarcoma (1 paper, 2015). A small round cell tumor that lacks morphologic, immunohistochemical, and electron microscopic evidence of neuroectodermal differentiation. "In summary, our studies identify a growth-promotional role for PIK3R3 in Ewing Sarcoma, and provide evidence that loss of PTEN expression may diminish responsiveness to vincristine and IGF-1R blockade." (PMID 25603314, 2015). "Our studies support a tumor-promotional role for PIK3R3 in Ewing Sarcoma." (PMID 25603314, 2015). "In the present manuscript, we examine the expression and role of two regulatory components of the PI3K signaling pathway, the activator PIK3R3 and the inhibitor PTEN, in Ewing Sarcoma." (PMID 25603314, 2015). "Our studies thus identify PIK3R3 and PTEN as modifiers of oncogenic phenotypes in Ewing Sarcoma, with potential clinical implications." (PMID 25603314, 2015). "In the present study, we identify variable expression of two modifiers of PI3K signaling activity, PIK3R3 and PTEN, in Ewing Sarcoma, and examine the consequences of this on PI3K pathway regulation and oncogenic phenotypes." (PMID 25603314, 2015). "Together, our findings indicate that PIK3R3 plays a growth-promotional role in Ewing Sarcoma, and suggest that this role is not strictly dependent on regulation of PI3K pathway activity." (PMID 25603314, 2015). "In the present study, we asked how PIK3R3, a regulatory component of the PI3 kinase complex, and the phosphatase and established tumor suppressor PTEN, contribute to the control of PI3K pathway activity and oncogenic phenotypes in Ewing Sarcoma." (PMID 25603314, 2015). "Our findings indicate that PIK3R3 plays a growth-promotional role in Ewing Sarcoma, but suggest that this role is not strictly dependent on regulation of PI3K pathway activity." (PMID 25603314, 2015). "Our studies indicate that PIK3R3 growth-promotional effects in Ewing Sarcoma are not strictly dependent on regulation of PI3K pathway activity, and may operate through alternative mechanisms." (PMID 25603314, 2015).
fibrolamellar carcinoma (1 paper, 2023). "PIK3R3 was elevated in hepatocholangial carcinoma compared with hepatocellular and fibrolamellar carcinoma." (PMID 37212524, 2023).
gastric adenocarcinoma (1 paper, 2012). "We examined the PIK3R3 mRNA expression of 126 gastric adenocarcinoma samples and matched non-neoplastic mucosa control gastric tissues, profiled on Affymetrix GeneChip Human Genome U133 Plus 2.0 arrays." (PMID 22876838, 2012).
Hepatic fibrosis (1 paper, 2025). The presence of excessive fibrous connective tissue in the liver. "A study on the efficacy of human AMSCs amniotic mesenchymal stem cell-derived extracellular vesicles (AMSC-EVs) in treating hepatic fibrosis revealed that AMSC-EVs delivered miR-200a into hepatocytes suppressing ZEB1/PIK3R3 axis." (PMID 39773634, 2025). "Suppression of the ZEB1/PIK3R3 axis reduces hepatic fibrosis by inhibiting its antifibrotic- effect." (PMID 39773634, 2025).
hidradenitis (1 paper, 2022). An inflammatory disease involving a pathogenic inflammatory response in the apocrine sweat gland. "The expression of the PIK3R3 gene has been found to be associated with skin lesions in human patients with hidradenitis, suggesting its role in skin development and hair growth." (PMID 36611750, 2022).
hyperlipidemia (1 paper, 2021). "Through the analysis of the hub genes in the network, it was found that targets such as PIK3R3, GNB5, and ESR1(ERα) have higher MCC values, suggesting that these genes were important targets for improving hyperlipidemia in PCE." (PMID 34925692, 2021). "Similarly, ESR1(ERα), MAOA, MGAM, PTK2, MMP1, GNB5, PIK3R3, and other targets had higher degree values, suggesting that these genes might be the core targets of PCE intervention in hyperlipidemia." (PMID 34925692, 2021).